H4C14 (H4 clustered histone 14)
Description:
Core component of nucleosome. Nucleosomes wrap and compact DNA into chromatin, limiting DNA accessibility to the cellular machineries which require DNA as a template. Histones thereby play a central role in transcription regulation, DNA repair, DNA replication and chromosomal stability. DNA accessibility is regulated via a complex set of post-translational modifications of histones, also called histone code, and nucleosome remodeling.
Synonyms: H4/N; H4F2; H4FN; HIST2H4; HIST2H4A; FO108; H4
Target class: Other nuclear protein
Gene: Protein-coding gene on chromosome 1 (149,832,657 to 149,839,767, forward strand). Ensembl gene ENSG00000270882.
Subcellular location: Nucleus; Chromosome
Pathways (Reactome):
Gene expression (Transcription): B-WICH complex positively regulates rRNA expression; DNA methylation; ERCC6 (CSB) and EHMT2 (G9a) positively regulate rRNA expression; MLL4 and MLL3 complexes regulate expression of PPARG target genes in adipogenesis and hepatic steatosis; NoRC negatively regulates rRNA expression; PRC2 methylates histones and DNA; RNA Polymerase I Promoter Escape; RNA Polymerase I Promoter Opening; RUNX1 regulates genes involved in megakaryocyte differentiation and platelet function; RUNX1 regulates transcription of genes involved in differentiation of HSCs; Regulation of endogenous retroelements by KRAB-ZFP proteins; Regulation of endogenous retroelements by Piwi-interacting RNAs (piRNAs); Regulation of endogenous retroelements by the Human Silencing Hub (HUSH) complex; SIRT1 negatively regulates rRNA expression; Transcriptional regulation by small RNAs
Chromatin organization: CHD1 and CHD2 subfamily; CHD6, CHD7, CHD8, CHD9 subfamily; ChAHP complex assembly; HATs acetylate histones; HDACs deacetylate histones; HDMs demethylate histones; Interaction of NuRD complexes with transcription factors; NuRD complex assembly; PKMTs methylate histone lysines; RMTs methylate histone arginines
DNA Repair: Cleavage of the damaged purine; Cleavage of the damaged pyrimidine; Nonhomologous End-Joining (NHEJ); Processing of DNA double-strand break ends; Recognition and association of DNA glycosylase with site containing an affected purine; Recognition and association of DNA glycosylase with site containing an affected pyrimidine; Recruitment and ATM-mediated phosphorylation of repair and signaling proteins at DNA double strand breaks
Cell Cycle: Condensation of Prophase Chromosomes; Deposition of new CENPA-containing nucleosomes at the centromere; G2/M DNA damage checkpoint; Inhibition of DNA recombination at telomere; Packaging Of Telomere Ends
Developmental Biology: Activation of anterior HOX genes in hindbrain development during early embryogenesis; Chromatin modifications during the maternal to zygotic transition (MZT); Replacement of protamines by nucleosomes in the male pronucleus
and 20 more pathways
Gene Ontology:
Molecular function: protein binding; RNA binding; structural constituent of chromatin; DNA binding; protein heterodimerization activity
Biological process: negative regulation of megakaryocyte differentiation; nucleosome assembly; chromatin organization; protein localization to CENP-A containing chromatin; telomere organization
Cellular component: CENP-A containing nucleosome; chromosome, telomeric region; extracellular exosome; membrane; nucleoplasm; nucleosome; nucleus; protein-containing complex; extracellular region; chromosome
Homologues: Paralogues in human: H4C1 (100% identical), H4C11 (100% identical), H4C12 (100% identical), H4C13 (100% identical), H4C15 (100% identical), H4C16 (100% identical), H4C2 (100% identical), H4C3 (100% identical), H4C4 (100% identical), H4C5 (100% identical), H4C6 (100% identical), H4C8 (100% identical), and 2 more.